BRD4 (bromodomain containing 4)
Diseases named in the same sentence as BRD4 in open-access papers (continued):
Sharing a sentence is not in itself a finding about the gene and the disease.
tumor (continued). "Our previous study demonstrated that BRD4 inhibition suppressed tumor growth in prostate cancer via the enhancement of FOXO116." (PMID 32303673, 2020). "It has been previously shown that BET inhibitors dissociated BRD4 from chromatin at the regulatory regions of multiple RTKs to reduce their expression level, thereby sensitizing a broad range of tumor cell lines to PI3K-Akt inhibitors." (PMID 33051401, 2020). "As an epigenetic regulator and transcription factor, BRD4, along with its chemical inhibitor JQ1, is strongly implicated in regulation of cell proliferation, survival and tumor growth in KRAS mutated NSCLC in a c-Myc-dependent manner." (PMID 32793596, 2020). "Mechanistically, PCAF acetylation of ISX at lysine 69 promotes the interaction with acetylated bromodomain‐containing protein 4 (BRD4) at lysine 332 in tumor cells, and the translocation of the resulting complex into the nucleus." (PMID 31908141, 2020). "As a crucial regulator for chromatin remodeling, BRD4 promotes tumor progression by regulating multiple genes." (PMID 32157097, 2020). "Univariate survival analysis revealed that, in addition to clinical stage, tumor differentiation, nervous invasion and vessel invasion, high BRD4 (HR = 3.321, p = 0.001) and CAV-2 expression (HR = 3.666, p < 0.001) predicted poor prognosis." (PMID 32099528, 2020). "Simultaneously, we demonstrated that IBET-151 treatment attenuates GLI1 transcription by reducing BRD4 occupancy on the GLI1 locus in both EAC47 cells derived from a patient tumor and OE33 cell line." (PMID 32913560, 2020). "Recent studies indicated that the maintenance of the protein levels of BRD4 or its bromodomain independent function in tumour cells contributes to BET resistance." (PMID 31937753, 2020). "Of the 76 paraffin-embedded tumor-tissue samples, high BRD4 protein level was found in 65.8% (50 of 76) of PC tissues, compared with only 43.4% (33 of 76) of normal tissues (p = 0.014)." (PMID 32099528, 2020). "The results from our VS-6063/JQ1-based in vivo analyses support a cooperative role of the integrin-FAK and BRD4/c-Myc axes in the TNBC tumor microenvironment." (PMID 33006750, 2020). "The mRNA expression of BRD4 was identified to be associated with tumor grade (WHO grade); BRD4 has the highest expression in GBM." (PMID 33135348, 2020). "Together, these data suggest that tumor cell sensitivity to co-inhibition of FAK and the BRD4/c-Myc axis is linked to the EMT program and its associated transcription factors." (PMID 33006750, 2020). "dBET6, a linker optimized derivative of dBET1, showed more activities in BRD4 degradation and tumor growth inhibition in cells and mouse models of acute lymphoblastic leukemia." (PMID 32404196, 2020). "Western blotting showed that BETd-260 treatment completely depleted BRD2, BRD3, and BRD4 proteins in the tumor tissue." (PMID 31653826, 2019). "(+)-JQ1 is an inhibitor of the tumor-driver bromodomain protein BRD4 and produces satisfactory effects because it efficiently increases apoptosis." (PMID 30988278, 2019). "The results showed that treatment with a single dose (5 mg/kg) of BETd-260 for 24 h significantly suppressed the expression of BRD2, BRD3 and BRD4 in tumor tissue of both HCC models." (PMID 31993368, 2019). "Overall, we can infer that JQ1 decreases tumor growth via ferroptosis mediated by BRD4 suppression in vivo." (PMID 30988278, 2019). "In vivo experiment, the combination therapy of PARPi and BRD4 inhibitor effectively prolonged tumor control in multiple patient-derived tumor xenograft models including HR proficient ovarian and breast cancers." (PMID 31737426, 2019). "BRD4 has been recognized as an important regulator in tumor biology due to its role in the regulation of gene expression." (PMID 30988278, 2019). "JQ1 and I‐BET were developed as potent targeted inhibitors of BET family members, including BRD4, for tumor therapy." (PMID 31832310, 2019).
tumor (continued). "In particular, a recent study demonstrated a direct role of BRD4 in ATCs, where its silencing significantly inhibited tumor growth both in vitro and in vivo." (PMID 31200515, 2019). "BRD4 has been found to modulate multiple aspects of tumor biology, including proliferation, migration, invasion, and survival." (PMID 30728036, 2019). "SF1126 is the first PI3K/BRD4 inhibitor reported by SignalRx Pharmaceuticals, Inc., blocking tumor growth in various preclinical mouse models." (PMID 30853982, 2019). "Since the effects of BET inhibitors are often through inhibition of the BET protein BRD4, we evaluated expression of hnRNPA1 and BRD4 in human tumor specimens." (PMID 31480735, 2019). "Because BRD4 densely occupies super enhancers, its inhibition reduces MYC transcription causing an anti-tumor effect." (PMID 31226848, 2019). "Here, we show that miR-3140, which was identified as a novel tumor suppressive miRNA by function-based screening of a library containing 1090 miRNA mimics, directly suppressed BRD4 by binding to its coding sequence (CDS)." (PMID 29540837, 2018). "(+)-JQ1, a BRD4 inhibitor firstly discovered as an anti-tumor agent, was later confirmed to be an anti-inflammatory compound." (PMID 30479742, 2018). "Combinations of HDAC inhibitors with JQ1, an inhibitor of bromodomain-containing acetylation reader proteins like BRD4, which promote especially the transcription of pro-tumorigenic genes, have shown efficacy in several tumor types." (PMID 29312470, 2018). "Taken together, downregulation of BRD4 contributed to miR-3140-mediated suppression of tumor cell growth." (PMID 29540837, 2018). "We revealed that miR-3140, identified as a novel tumor suppressive miRNA (TS-miRNA), repressed BRD4 directly by binding to its CDS." (PMID 29540837, 2018). "BRD4-amplified HGSOC tumors are mutually exclusive with BRCA1/2 mutations and therefore represent a tumor subtype with few therapeutic options beyond platinum-based chemotherapy." (PMID 30036377, 2018). "Transfection of siRNA targeting each BET family gene, especially si-BRD4, markedly inhibited tumor cell growth." (PMID 29540837, 2018). "The mRNA levels of BRD3 and BRD4 were significantly higher in primary of tumor (TP) versus normal tissue (NT), while there was no significant change of BRD2 mRNA levels in NT vs. TP." (PMID 29434197, 2018). "Although lapatinib exhibited anti-tumor activity against BRD4-amplified tumor models, and gave significant combination activity with AZD5153, further investigation will be required to interrogate the role of NRG1 as a therapeutic target." (PMID 30036377, 2018). "BRD4 expression correlated with larger tumor size (p = 0.0049), pre-menopausal status (p = 0.0018), and high Ki-67 proliferative index (p = 0.0009)." (PMID 30029633, 2018). "We tested the in vivo anti-tumor activity of AZD5153 on two BRD4-amplified patient-derived xenografts, OV0857F and HOXF062, as well as one non-amplified PDX OV2022F." (PMID 30036377, 2018). "The BRD4-NUT oncoprotein promotes tumor cell growth through the function of BRD4 as well as that of NUT16–18." (PMID 29540837, 2018). "The inhibitory action of BRD4 on tumor cell proliferation has been attributed to inhibition of the cMYC oncogene." (PMID 29156698, 2017). "Together, these data demonstrate that simultaneous inhibition of CDK9 and BRD4 acts synergistically on suppressing tumor proliferation." (PMID 29156698, 2017). "We revealed a direct role for BET proteins both in skeletal muscle and in the tumor, by showing direct recruitment of BRD4 and BRD2 at a subset of pro-atrophic genes and pro-cachectic mediators." (PMID 29167426, 2017). "Inhibition of tumour growth relative to untreated controls was observed, with pharmacodynamic evidence of BRD4 depletion in treated tumours seen." (PMID 28298557, 2017). "JQ1 abrogates Brd4-functions and inhibited tumor progression in xenograft models as well as in the recently developed LSL-MYCN;DBH-iCre neuroblastoma mouse model." (PMID 27769070, 2016).
tumor (continued). "While preparing our manuscript, two papers were published reporting that BRD4 is responsible for tumor growth in HCC." (PMID 27081696, 2016). "The epigenetic reader BRD4 is significantly overexpressed in tumor tissues than normal in three cohorts." (PMID 27081696, 2016). "We observed that BRD4 level was significantly related to histological type (P < 0.001), lymph node metastasis (P < 0.001), tumor stage (P < 0.0031) and differentiation (P = 0.031)." (PMID 26840017, 2016). "This is due to the low levels of prelamin A expression in the brain, and to the presence of a tumour protection mechanism mediated by bromodomain containing protein 4 (BRD4) in cells from individuals with HGPS (discussed in more detail later)." (PMID 27482812, 2016). "We further compared the proportion of BRD4 expression between tumor and para-tumor tissues, we found that BRD4hi level in NSCLC tissues accounted for 46.15% (96 of 208), which was higher than that in para-tumoral tissues (32.21%, 67 of 208) (p = 0.005)." (PMID 26840017, 2016). "BRD4 was weakly expressed in normal liver tissues and highly expressed in both primary tumor and adjacent liver tissues." (PMID 26575167, 2016). "For example, JQ1, a potent BRD4 inhibitor, has displayed anti-tumor activities in preclinical studies." (PMID 27631103, 2016). "MYCN-directed treatment by AuroraA- or Brd4-inhibitors resulted in significantly decreased cell proliferation in vitro and reduced tumor growth in vivo." (PMID 27769070, 2016). "Further we show that the presence of intact AP1 sites in the CRPV genome as well as of the E2 binding partner Brd4 is essential for tumor formation in the rabbit." (PMID 26727473, 2016). "We also demonstrate dual inhibition of mTOR and BRD4 led to a better anti-tumor effect in c-Myc overexpressing MCC tumors." (PMID 26536665, 2016). "Lack of response of MYC to Notch inhibition can be explained by the inactivate state of the Notch-dependent MYC long-range enhancer (NDME) in this tumor, which appears instead to rely on a BRD4-dependent long-range enhancer (BDME) defined previously in AML." (PMID 27148573, 2015). "We have paid close attention to several previous studies, which showed that BRD4 inhibitor seemed to be effective only at inhibiting primary tumor growth." (PMID 25603177, 2015). "Here we demonstrate that bromodomain inhibitors (BETi), JQ1, I-BET151, I-BET762, exert potent anti-tumour activity against primary and established OS cell lines, mediated by inhibition of BRD4." (PMID 25944566, 2015). "In most previous studies, BRD4 is thought to exist in two spliced isoforms with opposing roles in tumor growth and progression." (PMID 25603177, 2015). "Although BRD4 is a ubiquitous regulator, it also has gene-specific effects due to the presence of super-enhancer in tumor cells." (PMID 26397223, 2015). "In this paper, we demonstrate that BRD4 inhibition has a significant effect on CRC, and that it can curtail associated tumor metastasis." (PMID 25603177, 2015). "We demonstrate that inhibition of BRD4 results in suppression of tumor cell self-renewal, stem cell signaling, and induction of senescence in vitro and in vivo." (PMID 24796395, 2014). "It has recently been shown that BRD4 is enriched at super-enhancers that regulate key cell identity genes and tumor drivers." (PMID 24832099, 2014). "Previously our laboratory demonstrated that the two BRD4 isoforms have opposite effects on tumor progression with BRD4-LF suppressing tumor growth and dissemination and BRD4-SF promoting metastasis." (PMID 24260471, 2013). "The BET family member BRD4 plays an important role for survival of a number of diverse tumours due to its function promoting transcription of growth promoting and antiapoptotic genes." (PMID 23918227, 2013). "The inhibitors have demonstrated efficacy against several tumor types, including the highly refractory midline carcinomas that result from BRD4-NUT translocation fusion." (PMID 24260471, 2013).
tumor (continued). "Deletion of bromodomain II resulted in further suppression of primary tumor growth and lung metastasis mediated by Brd4 and also induced a conversion to a more epithelial state." (PMID 22295248, 2012). "In conclusion, our study not only reveals a novel enhancer-mediated transcriptional mechanism involving NR2F2 and BRD4 that activates BGN in PTC but also highlights BGN's dual role in promoting tumor cell-intrinsic aggressiveness and shaping the tumor immune environment." (PMID 41328346, 2026). "Importantly, we demonstrated that BRD4 inhibitor AZD5153 possesses potent activities in blocking tumor growth of both de novo NEPC and t-NEPC." (PMID 40370549, 2025). "Since UNI66 demonstrated no tumor growth inhibition, potentially attributable to solubility challenges in achieving effective treatment concentrations for zebrafish xenograft experiments, we employed JQ1, a widely recognized BRD4 inhibitor, for an in vivo experiment aimed at tumor suppression." (PMID 40308947, 2025). "Moreover, a combined therapy using cRGD-modified nanoparticles (cRGD-P) co-delivering doxorubicin (DOX) and BRD4 PROTAC degrader ARV-825 showed synergistic tumor inhibition and a better efficacy than the individual administration of these compounds." (PMID 41008623, 2025). "Additionally, LLC tumor–bearing BRD4 cKO mice had significantly lower baseline levels of both PMN-MDSCs and M-MDSCs in the spleen compared with WT mice." (PMID 40762981, 2025). "The combination of BRD4 inhibitors with anti-PD1 mAb therapy suggests a hypothesis that this synergistic approach will not only target the drivers of tumor growth and survival but strengthen a robust and effective antitumor immune response." (PMID 39816690, 2025). "In all models, BRD4 inhibition reduced tumor volumes, and in the 4T1 model treated with PLX51107, this effect reached statistical significance, suggesting that the reductions in MDSC numbers could be due to reduced tumor burden." (PMID 40762981, 2025). "UNI66, another inhibitor of BRD4, suppresses HR by inhibiting BRD4-mediated transcription of CtBP-interacting protein (CtIP) and RAD51, thereby inducing synthetic lethality in PARP1-deficient cells and enhancing tumor sensitivity to PARPis." (PMID 41190241, 2025). "Anti–PD-L1 therapy did not reduce tumor volumes of BRD4 WT mice but was effective in mice deficient in BRD4 in the myeloid compartment (WT + anti–PD-L1 vs. cKO plus anti–PD-L1, P < 0.05)." (PMID 40762981, 2025). "BRD4 inhibitors also decreased tumor cell secretion of GM-CSF." (PMID 40762981, 2025). "Inhibition of BRD4 significantly suppresses tumor growth and induces apoptosis in HCC models." (PMID 41323392, 2025). "In this trial concept, the invigorated immune system could act in synergy with increased antigen presentation by tumor cells stressed due to transcription defects induced by interference with the BRD4 function." (PMID 40699853, 2025). "Specifically, BRD4-NUT maintains tumor growth through a potent chromatin-modifying mechanism." (PMID 41348877, 2025). "BRD4 inhibition could theoretically prevent the release of tumor-derived soluble factors that are involved in the expansion and recruitment of MDSCs." (PMID 40762981, 2025). "In addition, BET inhibitors (RG6146 and JQ1) sensitize tumor cells to TNF-mediated cytotoxicity by blocking BRD4-dependent NF-κB survival programs in tumor cells." (PMID 41583469, 2025). "The loss of this tumor suppressor was reported to induce the transcriptional de‐repression of at least 25 HERV‐H loci, and the resulting ﻿HERV‐H transcripts colocalize with nuclear BRD4 foci and influence the downstream transcriptional network." (PMID 39992019, 2025). "BRD4 inhibitors block chemokine production by tumor cells, resulting in decreased MDSC migration." (PMID 40762981, 2025). "Nanostring tumor gene profiling reveals decreased myeloid cell infiltration after BRD4 inhibition." (PMID 40762981, 2025).
tumor (continued). "Importantly, aberrant BET activity, particularly that of BRD4, has been linked to the overexpression of oncogenes such as MYC, BCL-2, and NF-κB, which drive tumor proliferation, survival, and immune evasion." (PMID 41335282, 2025). "Aside from a putative suppressor of tumor growth, the long‐form BRD4 may impact cellular phenotype through regulation of expression of ECM molecules (e.g., collagen)." (PMID 40959971, 2025). "However, in BRD4 myeloid–deficient mice, single-agent anti–PD-L1 therapy resulted in reduced LLC tumor growth when compared with control treatment." (PMID 40762981, 2025). "This indicates that BRD4 may have a significant role in aggressive tumor progression and may be an effective therapeutic target for combating chemoresistant HNSCC." (PMID 40649963, 2025). "This underscores a BRD4-specific role in anti-tumor immunity, further supported by adoptive transfer studies, where BRD4 inhibition via the BRD4–p300 axis enhanced BATF expression, improving persistence and anti-tumor activity in adoptive T cell and CAR-T models." (PMID 41583469, 2025). "Additionally, BRD4 inhibition significantly reduced myeloid-derived suppressor cells (MDSCs) in the spleens and tumors of mice in multiple tumor models and also decreased the release of tumor-derived MDSC growth and chemotactic factors." (PMID 40762981, 2025). "Furthermore, our findings suggest a dependence of these tumor-specific TFs on the epigenetic landscape, demonstrated through their downregulation following BRD4 inhibition." (PMID 41323280, 2025). "However, results from the BRD4 ChIP-Seq on MDSCs from tumor-bearing mice revealed an enrichment of BRD4 on key MDSC genes, highlighting the importance of BRD4 in MDSC biology." (PMID 40762981, 2025). "As might be expected with a novel targeted agent, the combinatorial efficacy of BRD4 inhibitors and immune checkpoint inhibitors in solid tumors has been studied in the past and has been mostly attributed to direct tumor effects of BRD4 inhibition." (PMID 40762981, 2025). "Additionally, it has been reported that a positive regulation of CCBE1 by YAP1/TAZ/BRD4 and their pro-tumor lymphangiogenesis in colorectal cancer." (PMID 41184230, 2025). "To investigate whether BRD4 inhibition promoted ferroptosis in vivo, we established tumor xenografts with HCT116 cells in nude mice and treated these mice with vehicle, JQ1, RSL3, and a combination of JQ1 and RSL3 (JQ1 + RSL3), respectively." (PMID 41249136, 2025). "Given its high expression in tumour vascular systems and its positive correlation with invasive genes, we suggest that Brd4 may serve as a link between blood vessel and cell competition." (PMID 39010274, 2024). "The key mechanism of ARV-825 in tumor inhibition is the ubiquitination degradation of BRD4." (PMID 39140036, 2024). "In this study, we demonstrated that BETi, through the specific inhibition of the epigenetic reader BRD4, down-regulated the expression of inhibitory receptors and molecules that are involved in NK cell regulatory mechanisms, self-tolerance, and tumor immune escape." (PMID 38519469, 2024). "Of note, BRD4 is a bromodomain protein that plays a key role in epigenetic memory, and bromodomain inhibitors have been suggested as a possible therapeutic strategy in other tumor types." (PMID 38500181, 2024). "Furthermore, our observations through IHC staining indicated that MZ1 treatment significantly inhibited the expression of BRD4 and the proliferation marker Ki-67 in tumor tissues, in comparison to the control group." (PMID 38365636, 2024). "Furthermore, fusion calling from whole-genome sequencing of two paired datasets from tumor and normal liver DNA from the same tumor-bearing mice detected Brd4::Nutm1 as the only recurrent fusion gene in tumor tissues." (PMID 38724194, 2024). "Moreover, BET inhibitors, which target BRD4 and disrupt its interaction with acetylated histones, have shown promising anti-tumor effects in preclinical NSCLC models." (PMID 39457373, 2024).